MMP9 (matrix metallopeptidase 9)
Diseases named in the same sentence as MMP9 in open-access papers (continued):
Sharing a sentence is not in itself a finding about the gene and the disease.
tumor (continued). "We found that isothiocyanates harboring an –N=C=S group suppressed tumor metastasis by inhibiting FAK/MMP-9 activity and that the magnitude of the anti-tumor and anti-metastatic effects in vivo differed according to the isothiocyanate injected." (PMID 28969043, 2017). "Depletion of JUN and JUNB or RELA in tumor cells blocked the cooperative induction of MMP9 by the cytokines." (PMID 28423685, 2017). "Similar, the expression of MMP9 and the density of M2 macrophages in tumor stroma(r = 0.455; P < 0.001) and islets(r = 0.374; P < 0.001) also showed positive correlation respectively." (PMID 28423526, 2017). "MMP-2 and MMP-9 are the most widely studied and reported, with evidence for key roles in angiogenesis, tumor growth and extracellular matrix remodeling." (PMID 28241871, 2017). "In summary, isothiocyanates inhibit tumor growth and metastasis by suppressing MMP-9 activity/expression, an effect achieved by blocking the FAK/ERK/Akt and NF-κB/AP-1 pathways." (PMID 28969043, 2017). "The role of lipocalin-2/MMP-9 complex consists in prevention of MMP-9 degradation and thus in the strengthening of the role of MMP-9 as a factor involved in tumor progression." (PMID 29089666, 2017). "Aim of the present study is to determine if epithelial derived-MMP9 is responsible for this contrasting but defensive role of tumor suppressor in CAC." (PMID 27861153, 2017). "We then confirmed pro-angiogenic cytokines (IL8 and IL6), TIMP-2, and MMPs (MMP-2 and MMP-9) in the isolated tumor tissues by IHC." (PMID 28659184, 2017). "These processes mostly accompanied with tumor cell migration and matrix metalloproteinase-9 (MMP-9) mediated extracellular matrix degradation, which was similar to the CCR7 mediated lymph vessel intravasation process." (PMID 28114889, 2017). "In this study, we present evidence that TNC activates JNK/c-Jun signalling, resulting in induction of EMT and transcriptional activation of MMP9 to enhance the metastatic properties of tumour cells." (PMID 29088796, 2017). "Only have few studies have investigated the role of Rap1GAP in promoting the invasion of tumor cells via the upregulation of MMP9 secretion." (PMID 28009991, 2017). "The expression of cytokine epidermal growth factor, CXCL9, CCL25, and MMP9 were differently expressed between primary tumor and metastasis sites, especially when cocultured with MSCs, suggesting a crosstalk between MSCs and tumor cells." (PMID 28205428, 2017). "MMP-9 promotes the dissociation of EC from the basement membrane, which is essential for the induction of tumor angiogenesis." (PMID 28388546, 2017). "Exosomes from activated T cells promote tumor metastasis through upregulation of MMP9 protein levels in tumor cells via Fas signaling." (PMID 29137230, 2017). "MMP9 can promote tumour progression by degrading the extracellular matrix and facilitating cell migration, invasion and metastasis." (PMID 28109307, 2017). "A recent study also revealed that decreased H3K4me3 modification at the MMP9 promoter reduces MMP9 expression and inhibits tumor cell proliferation." (PMID 29228680, 2017). "Consistent with the in vitro experiments results, knockdown of FMNL3 in vivo also led to up-regulation of E-cadherin and down-regulation of Vimentin and MMP-9 in tumour cells in xenographs." (PMID 28198387, 2017). "Together, these data indicate both MMP3 and MMP9 are involved in the 3T3-A-EXO-mediated increase in 3LL tumor cell metastasis in vivo." (PMID 29137230, 2017). "The activity of MMP-9 facilitates the migration of tumor cells from the original site and induces inflammation." (PMID 29029486, 2017). "It restores MEC interaction with the matrix, opposes TGF-β signalling and MMP-9 proteolysis, which contributes to inhibition of tumour cell invasion." (PMID 28330493, 2017). "It suppresses E-cadherin, but increases matrix metalloproteinase-9 (MMP-9) expression and cell motility, which are each essential for tumor cell invasion." (PMID 28030810, 2017).
tumor (continued). "TAMs secrete a plethora of proangiogenic factors, such as vascular endothelial growth factor (VEGF), basic fibroblast growth factor (bFGF), and matrix metalloproteinase-9 (MMP9), which are all associated with tumor angiogenesis and metastasis." (PMID 27418133, 2016). "In both normal and tumor cells, MMP-9 has been shown to be secreted in response to EGFR activation via exogenous ligands." (PMID 27888810, 2016). "It was reported that PRO down-regulated endothelial MMP-9 expression and reduced the rate of human brain microvascular endothelial cells tubologenesis, potentially reducing tumour angiogenesis." (PMID 27899953, 2016). "In vivo treatment results also showed anti-tumor effcet was most obvious in FA-CD-PLLD/DOC/MMP-9 treated group by analysed tumor volume and PCNA expression." (PMID 27259274, 2016). "Our results suggest that zingerone possesses antiangiogenic activity by inhibiting the activities of MMP-2 and MMP-9 under hypoxic conditions during tumor progression." (PMID 27323807, 2016). "Myeloid-derived suppressor cells also participate in the promotion of angiogenesis in the tumour through the release of soluble factors like MMP9 and VEGF." (PMID 26913068, 2016). "Validation of Meta data showed that prognostic implications for OTSCC can be derived by evaluating E-cadherin and MMP9 expression at the invasive tumor front by a routine technique like immunohistochemistry." (PMID 27280700, 2016). "In this process, MMPs are activated and, in particular, the expression of MMP-2 and MMP-9 is upregulated within the tumor microenvironment." (PMID 27876012, 2016). "MMP-3 and MMP-9 originating from the tumor microenvironment, tumor cells, and stromal cells adjacent to the tumor cells help to facilitate EMT via invasion and metastasis behaviors." (PMID 26828526, 2016). "To examine the involvement of STAT3 activity in macrophage AEG-1-mediated MMP-9 up-regulation in tumor cells, we inhibited STAT3 activation in FaDu cells with AG490, which is a pharmacological inhibitor of the upstream STAT3 activator janus kinase." (PMID 27793010, 2016). "Take the uterus for examples, galectin-7 up-regulate MMP-9 expression, thereby promotes tumor progression and metastasis in cervical squamous carcinoma, while in normal uterus, it promotes uterine repair following menstruation." (PMID 27259255, 2016). "Together, these studies demonstrate that both tumor and stromal-derived MMP9 are necessary for successful metastatic tumor development." (PMID 26956475, 2016). "Another potential direct effect of neutrophils on tumour progression is secretion of matrix metalloproteinase-9 (MMP-9) enzymes." (PMID 27212807, 2016). "MMP-9 degrades basement membrane collagen, and accordingly promotes tumor cell invasion and metastasis, decreasing survival in many types of cancer." (PMID 27792998, 2016). "In contrast, the meta-analysis revealed that increased MMP-9 level indicate high T category (RR = 0.83, 95% CI: 0.73-0.94), tumor stage (RR = 0.72, 95% CI: 0.63-0.82) and poor OS (5-year overall survival, RR = 1.32, 95% CI: 1.19-1.48)." (PMID 26918342, 2016). "The characteristic distribution pattern of MMP9 in our series was found to be diffuse expression in both the tumor and stromal areas of OTSCC." (PMID 27280700, 2016). "During degradation of ECM, MMPs especially MMP-2 and MMP-9 contribute to the proteolysis of the ECM whose degradation products together with tumor cells take part in the VM formation." (PMID 27793002, 2016). "Using both in vitro and in vivo models, we demonstrate that Rab40b and its effector protein Tks5, regulates MMP2 and MMP9 targeting and secretion during cell invasion and tumor growth." (PMID 27789576, 2016). "In conclusion, in vitro and in vivo assays showed that FA-CD-PLLD/DOC/MMP-9 as the co-delivery of hydrophobic drug and gene can efficiently exert targeted anti-tumor effect." (PMID 27259274, 2016).
tumor (continued). "Although MMP-9 regulated HB-EGF release from THP-1, it is possible that the observed dependency of tumor cell proliferation on MMP-9 was the result of MMP-9 acting directly on the tumor cells versus the macrophages." (PMID 27888810, 2016). "In this study, N-cadherin affected tumor progression by potentiating MMP-9 signaling in a cross-talk regulatory mechanism." (PMID 27737648, 2016). "Among them, MMP-2 and MMP-9 play key roles in tumor invasion and metastasis because of their specificity for type IV collagen, which is the principal component of the basement membrane." (PMID 26993601, 2016). "Inhibitors of MMPs can weaken the MMPs roles in regulation of angiogenesis by decreasing MMP-9 expression, and consequently the inhibition of tumor growth." (PMID 27825139, 2016). "Tumor-associated neutrophils (TANs) are important for pro-matrix metalloproteinase-9 (pro-MMP9) release at the tumor site, especially at early stages of tumor development." (PMID 27618112, 2016). "AP-1 acts as a master regulator of tumor cell migration and invasion by targeting genes such as MMP9." (PMID 27777384, 2016). "MMP-9 plays a key role in tumour pathogenesis and progression and triggers the angiogenic switch during carcinogenesis." (PMID 27514308, 2016). "Our results demonstrate that MMP-2, MMP-7, and MMP-9 expressions correlate with various morphological features of the PDAC tumor such as inflammation, necrosis, and formation of the new blood vessels." (PMID 27429508, 2016). "Unfortunately, we found only four trials that analyzed the relationship between MMP-9 expression and tumor size, and their conclusions were inconsistent." (PMID 27310993, 2016). "Meanwhile our study showed that overexpression of HIF-2α enhanced the expression of MMP2 and MMP9, which are closely related to tumor metastasis, are also significant to EMT." (PMID 26842802, 2016). "In this study, we investigated the effect of N-cadherin on MMP-9-mediated cell invasion after treatment with PMA (a potent tumor promoter) or macrophage conditioned medium (CM) in NPC cells." (PMID 27737648, 2016). "Together, these studies demonstrate that MMP9 can be produced by both TAMs and tumor cells for cancer progression and metastasis." (PMID 27487154, 2016). "During tumor progression, neutrophil function is converted from tumor-suppressing to tumor-promoting, thus producing more MMP-9 but releasing much less NE and TRAIL." (PMID 27270316, 2016). "Other major upregulated transcripts include mmp9 and mmp13a, known matrix metalloproteinases involved in embryonic development and tumor cell motility." (PMID 26846883, 2016). "SH003 reduced expression levels of Ki67, p-VEGFR2 and MMP-9, and increased expression level of cleaved caspase-3 in tumor tissues." (PMID 27105528, 2016). "We further noticed that the proliferation marker Ki-67 and tumor-promoting factors (MMP9, CXCR4) were significantly downregulated by resveratrol in CRC cells." (PMID 26959057, 2016). "The expressions of MMP-2, MMP-7, and MMP-9 were mainly observed in tumor cells and peritumoral stroma." (PMID 27429508, 2016). "Polymorphonuclear leukocytes (PMNs or neutrophils) can produce matrix metalloproteinase-9 (MMP-9) to initiate angiogenesis in the development of tumor." (PMID 27270316, 2016). "MMP-2 and MMP-9 are collagenases which favor tumor growth and invasion by digesting the extracellular matrix surrounding the tumor tissue." (PMID 26911838, 2016). "Several possible molecular mechanisms underlying LCN2 functions in tumor progression have been demonstrated, including promotion of epithelial to mesenchymal transition (EMT) and modulation of matrix metallopeptidase (MMP)-9 activity." (PMID 26840566, 2016). "Matrix metalloproteinases (MMPs), including MMP-2 and MMP-9, play essential roles in regulating tumor metastasis and angiogenesis." (PMID 26646323, 2016).
tumor (continued). "The levels of MMP1, MMP2, and MMP9 were found to be highly expressed in immunohistochemistry analysis of tumor invasive front tissues of patients with HNSCC." (PMID 27570510, 2016). "We also explored the efficiency of NEAT1 on MMP-7 and MMP-9 expression, which all made sense in tumor metastasis, and results demonstrated silencing NEAT1 expression suppressed MMP-7 and MMP-9 protein expression both in A549 and H1299 cells." (PMID 27351135, 2016). "The potent tumor-promoting effects of NGAL can be explained by stabilizing gelatinase B (MMP-9) and inducing EMT in several malignant neoplasms, thereby enhancing the invasion ability." (PMID 27863382, 2016). "Other pro-tumorigenic functions of TAN have been reported, such as tumor cell invasion via secretion of elastases, MMP8, MMP9 and cathepsin G and tumor cell proliferation via COX-2-dependent prostaglandin E2 synthesis." (PMID 27259252, 2016). "MDSCs have also been shown to produce vascular endothelial cell growth factor (VEGF), β-fibroblast growth factor (β-FGF), VEGF analogue Bv8, and matrix metalloproteinase 9 (MMP9), all of which are essential for angiogenesis and tissue invasion at tumor sites." (PMID 27868073, 2016). "Clusters of VEGFR1+ HPCs expressing VLA-4, the fibronectin receptor, interact with resident fibroblasts to stimulate fibronectin production and secrete MMP9 to create fitting niches for the recruitment of disseminating CXCR4+ tumor cells." (PMID 28032860, 2016). "The increased MMP9 production is of particular interest because the role of MMP9 in promoting tumor growth is well-established." (PMID 27427906, 2016). "The matrix metalloproteinase (MMP9), a key factor that promotes tumor metastasis, was significantly higher in tumors derived from AR-V7-expressing cells than in the controls as determined by immunoblot analysis (p=0.012)." (PMID 27588408, 2016). "Previous studies showed that in addition of factors like VEGFA and bFGF, which promote tumor angiogenesis, myelomonocytic cells also produce EGF, HGF, MMP-9 and other cytokines that directly enhance the tumor cell survival, growth and invasion." (PMID 27391260, 2016). "Neutrophils accumulating in pre-metastatic lungs support tumor cell extravasation and proliferation by release of pro-metastatic proteins, e.g., Bv8, MMP9, S100A8, and S100A9." (PMID 28066438, 2016). "Expression of MMP-9 plays an important role in tumor angiogenesis as it enhances the availability of VEGF in malignant tumors." (PMID 27271600, 2016). "The expression of the molecules, including TNF‐α, IL‐1β, HIF‐1α, NF‐κB, VEGF, and MMP9 in tumor tissues was analyzed by the methods of immunohistochemistry and western blot." (PMID 27734611, 2016). "MMP2 and MMP9 have been shown to be crucial for the “angiogenic switch” that occurs upon the initiation of tumor vascularization." (PMID 26979530, 2016). "Inflammatory cell-derived MMP-9 promotes tumor invasion and angiogenesis by mediating the release of TGF-β and VEGF." (PMID 27271600, 2016). "Enhanced tissue expression as well as circulating levels of LCN2 and MMP9, or their complex, have been observed in several tumor entities." (PMID 27461255, 2016). "These include the oncogene MDM2 and various genes supporting cell proliferation (KI-67), apoptosis (Bax), tumor invasion and metastasis (MMP9) and tumor angiogenesis (VEGF), as well as the anti-apoptosis gene BCL-2." (PMID 26943040, 2016). "For example, MMP2 and MMP9 were upregulated in pre-cancerous nodules where they promoted a switch to an angiogenic phenotype, resulting in tumor transformation and growth." (PMID 26956475, 2016). "It is well-known that MMP-9 is a product of both tumor and stroma cells especially macrophages and plays a key role in cancer invasion, metastasis and angiogenesis." (PMID 27793010, 2016). "Previous studies have shown that the expression level of matrix metalloproteinase 9 (MMP-9) is important for tumor cell invasion, migration and metastasis." (PMID 27287327, 2016).
tumor (continued). "As known, TGFbeta1 and MMP-9 are primarily produced by TAMs compared to the other macrophage phenotypes and seem to be necessary to promote the migration and invasion of tumour cells." (PMID 27846260, 2016). "A mechanistic study showed that the activities of MMP-2 and MMP-9 in tumor cells were decreased by treatment with zingerone." (PMID 27323807, 2016). "MMP2 and MMP9 are belonging to matrix metalloproteinases family, which are vital in tumor invasion and heterogeneous adhesion." (PMID 27120794, 2016). "Of more than 20 known human MMPs, MMP2 and MMP9 appear most important for tumor invasion due to their ability to degrade the ECM and basement membrane." (PMID 27556184, 2016). "MMP9 has also been reported to accelerate tumor growth by facilitating angiogenesis in the tumor and is thought to promote tumor invasion in HNSCC cell lines." (PMID 26745629, 2016). "Abnormal expression of these factors as well as other carcinogenic factors, such as NF‐κB and MMP9, further promotes tumor progression." (PMID 27734611, 2016). "MDSCs were found to infiltrate into tumors and promote tumor angiogenesis by producing high levels of MMP9 and by directly incorporating into tumor endothelium." (PMID 27246354, 2016). "Activation of IL-7R increased the phosphorylation levels of downstream signaling proteins, including STAT5, AKT, and JNK, as well as the expression levels of intracellular molecules, such as CyclinD1 and MMP-9, in tumor cells." (PMID 27821177, 2016). "Pro-tumor neutrophils upregulate the expression of pro-metastatic proteins, e.g., Bv8, S100A8, and S100A9, but also VEGF and MMP9 in pre-metastatic lungs of IFN-deficient mice." (PMID 28066438, 2016). "The expressions of TNF‐α, MMP9, HIF‐α, VEGF, NF‐κB, and IL‐1β were associated with the infiltration of inflammatory cells and the inhibition rate of tumor cells." (PMID 27734611, 2016). "Although many types of cells can produce MMP-9, infiltrating neutrophils have been found to trigger angiogenesis in the development of tumor, and support metastatic initiation." (PMID 27270316, 2016). "We also investigated the role of miR-329 on expression of MMP-9 and MMP-7, which all play a key role on tumor metastasis, and results indicated miR-329 inhibited the mRNA expression of MMP-9 and MMP-7 both in A549 and H1299 cells." (PMID 26909600, 2016). "In contrast, down-regulation of MMP-2 and MMP-9 provides a preventive measure against tumor metastasis." (PMID 27144433, 2016). "In our identified feedback loop, macrophage-secreted MMP-9 was responsible for initial cleavage of HB-EGF from the macrophage surface, which in turn increased MMP9 expression in the tumor cells." (PMID 27888810, 2016). "BSG (CD147, EMMPRIN) is an inducer of tumor cell associated MMPs, including MMP1, MMP2, MMP3, and MMP9." (PMID 26769849, 2016). "Our results fit this mechanism well, since we found that there is a positive correlation between CD163+ macrophages and MMP-9 tumor levels, as demonstrated by Spearman analysis." (PMID 27462782, 2016). "Expression in these regions was comparable to strong expression seen in areas of degeneration of tumor containing macrophages, which are known to express MMP9 strongly." (PMID 27255663, 2016). "In this context we used MMP-9 as a tool to unmask the NPs and make these locally effective in the tumor cell vicinity." (PMID 27993133, 2016). "During cancer development, MMP2 and MMP9 degrade the basement membrane as well as promote tumor cell metastasis to distant tissues and/or organs." (PMID 26917087, 2016). "We also investigated the role of miR-134 on expression of MMP-7 and MMP-9, which all play a key role on tumor metastasis, and results indicated miR-134 inhibited the protein expression of MMP-7 and MMP-9 both in A549 and SPC-A-1 cells." (PMID 27166267, 2016). "MMP9 is a known target of FoxM1, a key transcription factor that regulates tumor invasiveness and metastasis." (PMID 27259271, 2016).